APLN (apelin)
Diseases named in the same sentence as APLN in open-access papers (continued):
Sharing a sentence is not in itself a finding about the gene and the disease.
infarction (8 papers, 2015 to 2025). A localised pathological necrosis of tissue resulting from obstruction of the blood supply usually by a thrombus, an embolus, or vascular torsion. "Conversely, apelin may help protect against dangerous ventricular arrhythmias by improving perfusion and left ventricular function, ensuring cardioprotective effect which reduces susceptibility to post-infarction ventricular arrhythmias." (PMID 41155377, 2025). "Our results showed that transplantation of Apelin-13-pretreated MSCs improved angiogenesis in mouse hearts following infarction." (PMID 35355588, 2022). "We tracked very few MSCs in the diseased heart at 28 days post-MI; however, the long-term survival of Apelin-13-pretreated MSCs in the mouse heart following infarction needs further investigation." (PMID 35355588, 2022). "Finally, Apelin diminished the infarct size and normalized the impaired cardiac function as indicated by rescuing of the decreased ejection faction and fractional shortening in MI mice." (PMID 29245958, 2017). "The regulatory effect of apelin has also been observed on the evolution and activity of the cardiovascular system; the apelin concentration was lower in patients with primary hypertension, ischaemic heart disease, or those who underwent infarction, compared with healthy individuals." (PMID 35011661, 2021). "Numerous experimental studies have confirmed the cardioprotective effects of both apelin and ELA in models of infarction and ischemia-reperfusion injury." (PMID 41155377, 2025). "In conclusion, our results reveal that Apelin activates AMPK to rejuvenate AMSCs by increasing autophagy and promotes cardioprotection following infarction in mice." (PMID 33738284, 2021). "Our study shows that pretreating MSCs with Apelin-13 greatly improves cell survival under SD/H challenge by downregulating mitochondrial fission via inhibition of the ERK signaling pathway and enhances cardiac function following infarction in mice." (PMID 35355588, 2022). "In this study, we investigated whether Apelin regulates MSC senescence and whether its overexpression could rejuvenate aged MSCs (AMSCs) to improve cardiac protection following infarction in mice." (PMID 33738284, 2021).
oral squamous cell carcinoma (8 papers, 2014 to 2025). "A clinical study showed that Apelin up-regulation is associated with a poor prognosis in oral squamous cell carcinoma patients." (PMID 27733135, 2016). "Notably, apelin expression has been significantly linked to tumor recurrence and disease-free survival in oral squamous cell carcinoma (OSCC)." (PMID 39684225, 2024). "Apelin expression is related to oral squamous cell carcinoma hypoxia, and circulating apelin concentration is related to C-reactive protein in gastric and esophageal cancers." (PMID 34778094, 2021). "Another group demonstrated the prognostic significance of apelin expression in oral squamous cell carcinoma as well." (PMID 24962866, 2014). "In oral squamous cell carcinoma tissue the expression of apelin-36 was very weak." (PMID 29875677, 2018).
Parkinson disease (8 papers, 2019 to 2026). A progressive degenerative disorder of the central nervous system characterized by loss of dopamine producing neurons in the substantia nigra and the presence of Lewy bodies in the substantia nigra and locus coeruleus. "Apelin has also been implicated in many neurological disorders such as Alzheimer’s, Parkinson’s, and Moyamoya diseases." (PMID 35725619, 2022). "The same group was able to show also that Apelin can improve memory and cognitive deficits in a Parkinson’s disease model treated with 6-hydroxydopamine (6-OHDA)." (PMID 36421846, 2022). "For example, it has been reported that apelin-13 improves stress-induced cognition memory impairment in rats, and significantly reduces cognitive impairments in Parkinsonism rats." (PMID 31040784, 2019). "In line with this, apelin is a highly potent neuroprotective agent and should be further explored as a potential treatment under pathological conditions, such as brain injuries, and also Parkinson’s and Alzheimer’s disease." (PMID 36611944, 2022). "Deimination of the apelin signalling pathway in hypoxia may be of considerable interest; deimination has also been identified in pre-motor Parkinson’s disease." (PMID 35563075, 2022).
renal cell carcinoma (8 papers, 2019 to 2025). "In our study, we provide a comprehensive characterisation of APLNR and APLN expression in renal cell carcinoma." (PMID 30783205, 2019). "To directly correlate Apelin expression with anti‐angiogenic benefits, we accessed a cohort of renal cell carcinoma patients who received anti‐angiogenic sunitinib monotherapy." (PMID 31267692, 2019). "The aim of this study is to investigate the expression of APLN (apelin) and APLNR in patients with renal cell carcinoma (RCC), and its association with clinicopathological parameters and survival." (PMID 30783205, 2019). "Further, elevated Apelin levels in serum samples from renal cell cancer patients treated with sunitinib as a single agent were associated with a worse prognosis." (PMID 31267692, 2019). "Moreover, high apelin levels correlated with poor prognosis of renal cell carcinoma patients on sunitinib therapy." (PMID 33707612, 2021). "In renal cell carcinoma, combined low levels of VEGF and Apelin in sunitinib‐treated patient serum correlated with a 6‐fold longer progression‐free survival compared to patients with high levels of both VEGF and Apelin." (PMID 31318171, 2019).
acute kidney injury (7 papers, 2014 to 2025). Sudden and sustained deterioration of the kidney function characterized by decreased glomerular filtration rate, increased serum creatinine or oliguria. "Taken together, these studies suggest that modulating apelin levels may exert a therapeutic potential in preventing contrast-media-induced acute kidney injury." (PMID 41515992, 2025). "Similarly, in a murine model of contrast-induced acute kidney injury, it was shown that apelin has a renoprotective effect." (PMID 41515992, 2025). "Since the local RAS is obviously overactivated in patients with renal failure, it seems that the induction of the APLN/APLNR axis may influence the AngII-mediated pathophysiological effects." (PMID 33255902, 2020). "Lack of correlation between apelin-36 levels and daily urine output in our study may be due to blunted diuretic effect of apelin-36 in patients with renal failure who are supposed not to respond to decreased ADH levels." (PMID 24433492, 2014).
cardiomyopathy (7 papers, 2017 to 2025). A disease of the heart muscle or myocardium proper. "In addition, the hippo, oxytocin, and apelin signaling pathways were found to be deregulated, as well as the cardiomyopathy pathways." (PMID 37190014, 2023). "In males, only six pathways were found to be in common to all three models (apelin signaling, insulin signaling, focal adhesion, Huntington disease, oxytocin signaling and thermogenesis), none of which is directly related to cardiomyopathy or ISRmt." (PMID 37691621, 2023). "Similarly, previous studies have demonstrated that apelin, the first ligand of APJ, attenuates NLRP3 inflammasome activation in rodent models of acute lung injury, cardiomyopathy, and subarachnoid hemorrhage." (PMID 37540330, 2023).
liver cancer (7 papers, 2017 to 2024). An epithelial or non-epithelial malignant neoplasm that arises from the liver. "The model genes were mainly enriched in the apelin‐HDAC5‐KLF2 angiogenesis axis and mediated the occurrence of the PI3K‐AKT signalling pathway as well as the MAPK signalling pathway, providing direction for targeting the apelin/APJ pathway in liver cancer." (PMID 39434201, 2024). "Osteopontin, a glycoprotein of the extracellular matrix, and apelin, an endogenous peptide expressed in numerous tissues able to regulate physiological and pathological processes, turn out to have a potential role in liver cancer development and progression." (PMID 35429302, 2022). "APLN protein expression was assessed in multiple liver cancer cell lines and one immortalized liver epithelial cell line (MIHA) and four normal human liver tissues by western blot." (PMID 31410213, 2019). "APLN protein was readily expressed in all liver cancer cell lines, whilst no or very low expression was observed in normal liver tissues or MIHA cells." (PMID 31410213, 2019). "The functions of apelin in liver cancer are still not clear." (PMID 28484393, 2017).
myocardial ischemia (7 papers, 2013 to 2024). A disorder of cardiac function caused by insufficient blood flow to the muscle tissue of the heart. "Using a genetic model, loss of apelin exacerbated myocardial ischemia-reperfusion injury associated with compromised activation of the MEK1/2–ERK1/2 signaling pathway." (PMID 24695532, 2014). "Taken together, these data demonstrated that the Apelin overexpression protects against the diabetic myocardial ischemia reperfusion injury by inhibiting apoptosis and oxidative stress via PI3K and p38MAPK pathway in diabetic IRI rats." (PMID 33342766, 2020). "Apelin is highly expressed in the cardiovascular system where it exerts protective effects, including the dilation of blood vessels to reduce blood pressure, improvements to heart function, the inhibition of myocardial ischemia injury and the promotion of angiogenesis." (PMID 23403698, 2013). "Apelin is an endogenous ligand for the angiotensin-like 1 receptor (APJ) and has beneficial effects against myocardial ischemia/reperfusion injury." (PMID 24039710, 2013).
non-small cell lung carcinoma (7 papers, 2014 to 2023). A group of at least three distinct histological types of lung cancer, including non-small cell squamous cell carcinoma, adenocarcinoma, and large cell carcinoma. "Levels of APLN mRNA expression are higher in non-small cell lung cancer tissue than those in normal lung tissue and upregulation of APLN protein expression is related to poor overall survival of patients." (PMID 36632453, 2023). "In non-small cell lung cancer, apelin was overexpressed in tumor tissue at the mRNA level, as well as at protein level detected by immunohistochemistry." (PMID 31547096, 2019). "APLN levels increased in non-small cell lung cancer samples in comparison to normal lung tissue and high apelin levels were related to poor overall patient survival." (PMID 30127323, 2018). "High APLN levels in non-small cell lung cancer patients were correlated with high micro-vessel density and high APLN serum levels were also correlated with disease progression in a study that examined patients that suffered from either lung, gastrointestinal, breast, prostate or gynaecologic cancer." (PMID 28487489, 2017). "In non-small-cell lung carcinoma (NSCLC), APLN mRNA levels were significantly increased in tumor samples compared with normal lung tissue, and high APLN protein levels were associated with elevated microvessel densities and poor overall survival." (PMID 36614283, 2023).
osteoarthritis (7 papers, 2019 to 2025). A noninflammatory degenerative joint disease occurring chiefly in older persons, characterized by degeneration of the articular cartilage, hypertrophy of bone at the margins and changes in the synovial membrane. "APLN also plays an important role in retinal vascularization, while also impacting the progression of osteoarthritis by regulating VEGF-dependent angiogenesis and mir-150-5p expression." (PMID 37322431, 2023). "We also found significantly higher levels of APLN and Ang1 expression in synovial fluid from RA patients compared with those with osteoarthritis." (PMID 34659230, 2021). "In view of the importance of synovial cells in OA pathogenesis, we explored the crosstalk between APLN and IL-1β in human osteoarthritis synovial fibroblasts (OASFs)." (PMID 32420902, 2020).
Arrhythmia (6 papers, 2012 to 2023). Any cardiac rhythm other than the normal sinus rhythm. "More importantly, apelin decreased (P < 0.0001) the incidence arrhythmia inducibility (~44% to 0%) in association with decreased (P = 0.0039) arrhythmia duration (11.4 ± 4.0 s vs. 2.1 ± 0.8 s) compared with baseline (before apelin)." (PMID 32879139, 2020). "This latter finding can help explain the ability of apelin to increase atrial refractoriness and prolong APDs ), actions which are expected to reduce arrhythmia vulnerability." (PMID 32879139, 2020). "The purpose of this study is to investigate the potential utility of apelin as a marker of arrhythmia recurrence after direct-current cardioversion (DC)." (PMID 29721104, 2018). "The apelin role in the pathophysiology of heart rhythm disorders is considered, although the reports are scarce so far." (PMID 29721104, 2018). "The results of our study confirm the important role of apelin in the pathophysiology of cardiac arrhythmias." (PMID 29721104, 2018). "Low plasma apelin is an independent prognostic factor for arrhythmia recurrence in the patients with AF under antiarrhythmia medication." (PMID 22655211, 2012). "Patients with apelin levels below the median showed a hazard ratio of 3.1 of arrhythmia recurrence compared to those with high apelin levels." (PMID 22655211, 2012). "Moreover, when arrhythmias were observed in the presence of apelin, the dominant frequencies were reduced; as expected, none of the sedentary control mice showed evidence of inducibility (data not shown)." (PMID 32879139, 2020). "Therefore, we set out to directly examine connections between apelin and atrial electrophysiological properties as well as arrhythmias." (PMID 32879139, 2020). "In addition, our study is possibly the first to show that apelin directly modulates arrhythmia inducibility, with acute administration protecting against reentry arrhythmias in vivo and ex vivo by increasing both CV and APD." (PMID 32879139, 2020). "It was shown that the median, initial apelin level was significantly lower in patients who maintained sinus rhythm during the 3-month follow-up after the successful cardioversion, compared with patients in whom cardioversion was ineffective or who presented an arrhythmia recurrence." (PMID 29721104, 2018). "In conclusion, in our study, proBNP was not a marker of arrhythmia recurrence whereas higher apelin concentration at the admission indicated patients in whom DC was not effective or they had an arrhythmia recurrence within a month-period observation." (PMID 29721104, 2018). "According to our knowledge, the level of apelin has been investigated only in the patients with AF, and other forms of arrhythmia have not been investigated." (PMID 22655211, 2012). "Patients with persistent/permanent AF were not included in this study because we wanted to study if apelin is reduced in the setting of paroxysmal AF and therefore if it potentially can be used for AF detection (e.g., in patients after cryptogenic stroke with no symptoms of arrhythmia)." (PMID 34712712, 2021).
autosomal dominant polycystic kidney disease (6 papers, 2019 to 2022). Autosomal dominant form of polycystic kidney disease. "Serum apelin levels have been reported to be reduced in patients with autosomal dominant polycystic kidney disease and increased in patients with stage-5 CKD, even after treatment with blood and peritoneal dialysis." (PMID 32713238, 2020). "In the kidney, plasma apelin levels are significantly lower in patients with autosomal dominant polycystic kidney disease compared with controls, and apelin levels correlated with estimated glomerular filtration rate." (PMID 31492821, 2019). "Moreover, autosomal dominant polycystic kidney disease (ADPKD) patients were characterised by lower apelin levels and higher copeptin levels when compared with healthy subjects (HS)." (PMID 36553076, 2022). "Copeptin is measured as an alternative to vasopressin, which plays a detrimental role in autosomal dominant polycystic kidney disease (ADPKD), and apelin regulates angiogenesis and stimulates endothelial cell growth and migration." (PMID 36551927, 2022).
bladder cancer (6 papers, 2019 to 2025). "It is urgent to conduct cell experiments in vitro and animal experiments in vivo to comprehend the underlying mechanism of apelin's upstream and downstream interactions in muscle-invasive bladder cancer progression." (PMID 30984306, 2019). "In bladder cancer, APLN was upregulated in tumor tissues compared with matched adjacent noncancer tissues, especially in the high tumor stage, distant metastasis, and vascular invasion." (PMID 36614283, 2023). "Subsequently, the correlation of apelin expression with the clinicopathological features of bladder cancer patients was analyzed." (PMID 30984306, 2019). "In this study, we analyzed apelin levels in bladder cancer and matched paracarcinoma tissues." (PMID 30984306, 2019). "Although we did not study the underlying mechanism that how apelin could promote the progression in bladder cancer, our data about apelin expression and clinicopathological features showed that apelin was a therapeutic and management target which was consistent with their findings." (PMID 30984306, 2019). "Until now, no study has analyzed apelin expression among bladder cancer and matched paracarcinoma tissues." (PMID 30984306, 2019).
Cognitive impairment (6 papers, 2019 to 2024). Abnormal cognition is characterized by deficits in thinking, reasoning, or remembering. "Apelin could be serve as independent biomarker for T2DM-associated cognitive impairment for early diagnosis." (PMID 35610700, 2022). "The additional behavioral results further corroborate the notion that Apelin-13 exerts an ameliorative effect on cognitive impairment through the Nrf2-HO1 pathway." (PMID 38790466, 2024). "In summary, our data indicate that the intranasal administration of Apelin-13 effectively improves cognitive impairment in an STZ-induced animal model of AD." (PMID 38790466, 2024). "In summary, our study demonstrates that intranasal administration of Apelin-13 effectively improves cognitive impairment in an STZ-induced AD model by enhancing synaptic plasticity and modulating the Nrf2-HO1 pathway to reduce oxidative stress." (PMID 38790466, 2024). "We also explored serum apelin as a biomarker and protective molecules for cognitive impairment in T2DM." (PMID 35610700, 2022). "Apelin-13 was administered intranasally, and cognitive impairment was assessed using standardized behavioral tests, primarily, behavioral assessment, histological analysis, and biochemical assays, in order to evaluate synaptic plasticity and oxidative stress signaling pathways." (PMID 38790466, 2024). "Previous studies have explored the role of apelin in cognitive regulation, with evidence linking plasma apelin-13 levels to cognitive impairments, including attention-deficit/hyperactivity disorder (ADHD) and environmental factors influencing cognitive function." (PMID 39769424, 2024). "Apelin might has protective effect against cognitive impairment and serve as a serum biomarker of T2DM." (PMID 35610700, 2022). "However, whether apelin-13 can protect neurons to ameliorate cognitive deficits in AD by inhibiting the inflammatory response remains largely unknown." (PMID 31040784, 2019). "However, whether apelin-13 can ameliorate cognitive impairments of AD rats by attenuating inflammatory response as well as the underling neural mechanism are still largely unknown." (PMID 31040784, 2019). "Therefore, one can explain the effect of apelin-13 on the cognitive impairment of STZ rats." (PMID 31040784, 2019). "While the expression of both Apelin and APLNR decreases with increasing age, agonism of apelin receptors produces beneficial effects in fibrotic, cardiovascular, and cognitive disorders." (PMID 37315204, 2023).